LZIC (leucine zipper and CTNNBIP1 domain containing)
Synonyms: MGC15436
Tractability: PROTAC: ubiquitination databases record sites on it; its protein half-life has been measured.
Gene: Protein-coding gene on chromosome 1 (9,922,113 to 9,943,407, reverse strand). Ensembl gene ENSG00000162441.
Subcellular location (Human Protein Atlas): Nucleoplasm; Cytosol
Gene Ontology:
Molecular function: protein binding; beta-catenin binding
Biological process: response to ionizing radiation
Genetic constraint (gnomAD): Loss-of-function variants: 16 observed, 12.05 expected, observed/expected ratio (o/e) 1.33, 90% interval 0.89 to 1.86. The upper end of that interval is the gene's LOEUF score, 1.86, which puts it in group 6 of 6, group 1 being the genes least tolerant of losing a copy. Missense variants: 116 observed, 143.92 expected, observed/expected ratio (o/e) 0.81, 90% interval 0.69 to 0.94. Synonymous variants: 36 observed, 49.56 expected, observed/expected ratio (o/e) 0.73, 90% interval 0.56 to 0.96.
Homologues: Orthologues: chimpanzee LZIC (100% identical), macaque LZIC (100% identical), pig LZIC (98% identical), rabbit LZIC (97% identical), rat Lzic (96% identical), guinea pig LZIC (95% identical), mouse Lzic (94% identical), zebrafish lzic (85% identical), tropical clawed frog lzic (81% identical), dog LZIC (79% identical), Caenorhabditis elegans ZK1248.19 (32% identical). Paralogues in human: CTNNBIP1 (15% identical).
Diseases named in the same sentence as LZIC in open-access papers:
LZIC is named in the same sentence as 8 diseases in open-access papers, as found by Europe PMC text mining. Sharing a sentence is not in itself a finding about the gene and the disease. The quoted sentences say what the papers report.
Alzheimer disease (1 paper, 2025). A progressive, neurodegenerative disease characterized by loss of function and death of nerve cells in several areas of the brain leading to loss of cognitive function such as memory and language. "In Alzheimer's disease, the hub genes TNFRSF9, LZIC, CD30, SLC45A1, GPR157, and SLC25A33 are implicated in immune regulation, cellular transport, neuronal signaling, and mitochondrial function." (PMID 40104076, 2025).
clear cell renal carcinoma (1 paper, 2019). A malignant epithelial neoplasm of the kidney characterized by the presence of lipid-containing clear cells within a vascular network. "However, even at this early stage, our data are suggestive of the usefulness of LZIC as a biomarker for patient stratification, given that its expression is strongly correlated with survival of patients suffering from clear cell renal carcinoma." (PMID 30973299, 2019). "Although LZIC RNA expression correlated with poor patient survival for a range of cancers, the most striking effect was observed for the clear renal cell carcinoma and neuroendocrine tumors, in which reduction of LZIC expression correlated with a severe decrease in average patient survival times." (PMID 30973299, 2019).
endothelial dysfunction (1 paper, 2025). In vascular diseases, endothelial dysfunction is a systemic pathological state of the endothelium (the inner lining of blood vessels) and can be broadly defined as an imbalance between vasodilating and vasoconstricting substances produced by (or acting on) the endothelium. "The top hub genes identified were TNFRSF9, LZIC, TNFRSF8, SLC45A1, GPR157, and SLC25A33, which are induced by P. gingivalis and F. nucleatum and are responsible for endothelial dysfunction in brain cells." (PMID 40104076, 2025). "The top hub genes were TNFRSF9, LZIC, TNFRSF8, SLC45A1, GPR157, and SLC25A33, induced by P. gingivalis and F. nucleatum responsible for endothelial dysfunction in brain cells." (PMID 40104076, 2025). "Similarly, our study revealed genes like TNFRSF9, LZIC, TNFRSF8, SLC45A1, GPR157, and SLC25A33 that contribute to endothelial dysfunction in brain cells due to P. gingivalis and F. nucleatum." (PMID 40104076, 2025).
gastric cancer (1 paper, 2010). A primary or metastatic malignant neoplasm involving the stomach. "Protein LZIC ([Swiss-Prot:Q8WZA0], leucine zipper and ICAT homologous domain-containing protein; spot 151) is ubiquitously expressed (the highest level in the kidney); and it seems to be up-regulated in gastric cancers." (PMID 21073729, 2010).
pancreatic cancer (1 paper, 2011). "The expression of LZIC, FXR, SCAMP1, and SULT1E1 was significantly higher in pancreatic cancer tissues with LN metastasis than in pancreatic cancer tissues without LN metastasis." (PMID 21364590, 2011). "In summary, microarrays together with real-time PCR validation results clearly show that the expression of LZIC, FXR, SCAMP1, and SULT1E1 were confirmed to be significantly higher in pancreatic cancer tissues with LN metastasis than in pancreatic cancer tissues without LN metastasis." (PMID 21364590, 2011).
cancer (1 paper, 2019). A tumor composed of atypical neoplastic, often pleomorphic cells that invade other tissues. "Our findings suggest that LZIC is functionally involved in cellular response to IR, and its expression level could serve as a biomarker for patient stratification in clinical cancer practice." (PMID 30973299, 2019). "Finally, analysis of patient databases identified a positive correlation between LZIC expression and average patient survival time in a number of cancers, suggesting that LZIC expression could serve as a biomarker for patient stratification." (PMID 30973299, 2019).
LZIC also shares sentences with these, for which no sentence is quoted: neuroendocrine tumors (1 paper); tumor (1).